CSF1R (colony stimulating factor 1 receptor)
Diseases named in the same sentence as CSF1R in open-access papers (continued):
Sharing a sentence is not in itself a finding about the gene and the disease.
glioblastoma (continued). "In particular, inhibition of CSF1R (by the small-molecule BLZ945 treatment) in TAMs has been a promising intervention for glioblastoma (GBM) in mice; however, persistent usage of CSF1R inhibition can lead to drug resistance in mice." (PMID 35800363, 2022). "The modulation of CSF-1R signaling was shown to have significant impacts on the number and distribution of macrophages in a study of glioblastoma multiforme (GBM)." (PMID 35326625, 2022). "The CSF-1R inhibitor BLZ-945 reduced M2 macrophages when radiation increased in an orthotopic immunocompetent glioblastoma model." (PMID 35203505, 2022). "In previous studies, CSF-1R inhibition was shown to target pro-tumorigenic TAMs in glioblastoma and pancreatic tumor models in mice." (PMID 35821822, 2022). "Our results identify CSF1R as a promising therapeutic target for glioblastoma, potentially in combination with PD1 inhibition." (PMID 34063518, 2021). "A noteworthy observation was that the molecular targets of our compounds, i.e., CSF1R and PD-1, were detected in newly diagnosed and progressive glioblastoma." (PMID 34063518, 2021). "Macrophages and microglia accumulate with glioblastoma progression and can be targeted via inhibition of Colony-Stimulating Factor-1 Receptor (CSF-1R) to regress high-grade tumors in animal models of glioblastoma." (PMID 35008238, 2021). "Inhibition of the CSF-1 receptor (CSF-1R) enhanced sensitivity to irradiation by altering both the recruitment and the phenotype of myeloid-derived cells recruited to the irradiated glioblastoma." (PMID 33572835, 2021). "We investigated paired human glioblastoma samples from primary and subsequent progressive disease for the presence of CSF1R, CD204, CD163, PD1, PD-L1, CD3, CD4, and CD8." (PMID 34063518, 2021). "Though the CSF-1/CSF-1R pathway is required for TAM recruitment and survival, the inhibition of CSF-1R by BLZ945 was shown to repolarize TAMs in a glioblastoma multiforme mouse model." (PMID 34988021, 2021). "There are many approaches to targeting TAMs in glioblastoma, one of which is inhibition of colony stimulating factor 1 receptor (CSF-1R), an important receptor for macrophage differentiation and survival." (PMID 34054867, 2021). "Despite the promising results in pre-clinical models, no objective response was observed in a phase II study (NCT01349036) of a CSF1R inhibitor in patients with recurrent glioblastoma." (PMID 33374253, 2020). "Pexidartinib, an inhibitor of CSF-1R, augmented antitumor immune responses when combined with radiotherapy in glioblastoma models." (PMID 30853982, 2019). "Lastly, CSF1R inhibition significantly reduced established tumours and increased disease-free survival in mouse model for glioblastoma." (PMID 30577495, 2018). "In an in vitro co-culture system, inhibition of microglia migration by blockage of colony stimulating factor 1 receptor (CSF-1R) strongly suppressed glioblastoma invasion." (PMID 24675569, 2014). "Herein, a theranostic nanoplatform for the second near‐infrared window (NIR‐II) fluorescence imaging‐guided membrane‐targeted mild photothermal‐immunotherapy of glioblastoma using genetically engineered CSF1R/IL12‐macrophage membrane (MM)‐liposome hybrid nanovesicles, is reported." (PMID 40279543, 2025). "Given that TGF-β signaling and ECM remodeling are crucial in fibrosis-associated glioblastoma recurrence, strategies targeting fibrosis-related pathways have shown potential in enhancing the efficacy of anti-CSF-1R therapy and in reducing glioblastoma recurrence in preclinical models." (PMID 40076738, 2025). "Importantly, the inhibition of colony-stimulating factor 1 receptor (CSF-1R) signaling reduces the ability of glioblastoma multiforme stem cells to evade immune responses." (PMID 41368628, 2025).
glioblastoma (continued). "Despite promising preclinical results, CSF-1R inhibitors have shown limited efficacy in clinical trials for glioblastoma as in fact resistance to CSF-1R blockade is often observed, driven by compensatory mechanisms within the TME, including increased insulin-like growth factor-1 (IGF-1) signaling." (PMID 39457693, 2024). "As selective CSF1R inhibitors, such as pexidartinib, were shown to reduce the number of CD14dimCD16+ blood monocytes in patients with glioblastoma, this paper explores whether REG, which also inhibits CSF1R, has a similar effect." (PMID 37013652, 2023). "In a current clinical study, the combination of radiation and CSF-1R inhibitor is being tested in glioblastoma, and a Phase Ib/II study of combined PLX3397, radiation therapy, and temozolomide in patients with primary glioblastoma (NCT01790503) recently completed recruitment." (PMID 35203505, 2022). "Similarly, the effectiveness of radiotherapy and tyrosine kinase inhibitors in preclinical glioblastoma models, when CSF1R is inhibited, seems to be mediated by TAMs re-education." (PMID 35664746, 2022). "Taken together, our study indicates that CSF1R inhibition might be a promising therapeutic strategy for clinical translation in glioblastoma." (PMID 34063518, 2021). "Although in preclinical models of glioblastoma, targeting TAMs and microglia using CSF1R inhibitor combined with radiotherapy could enhance survival, might be not suitable for AML patients and impairs anti-tumor immune response." (PMID 33648605, 2021). "Interestingly, Ali and colleagues investigated different combinatorial therapies, considering CSF-1R, PD-1 and other targets, in glioblastoma and highlighted the importance of the therapy-induced time-dependent changes in TME cells." (PMID 34950148, 2021). "In mice, CSF-1R inhibition re-educates macrophages to adopt an anti-tumor phenotype, leading to tumor regression and increased survival, with a particularly profound effect in proneural glioblastoma." (PMID 34054867, 2021). "In this study, we present a novel hydroxyl dendrimer‐mediated immunotherapy to deliver CSF‐1R inhibitor BLZ945 (D‐BLZ) from systemic administration selectively to TAMs in glioblastoma brain tumors to repolarize the tumor immune environment in a localized manner." (PMID 34027092, 2021). "Importantly, analyses in two independent glioblastoma models revealed that conditions in which CSF1R inhibition leads to TAM depolarization show higher efficacy compared to TAM depletion." (PMID 31396225, 2019). "Given the promising results of TAM-targeted therapies with the CSF1R inhibitor BLZ945 in a mouse model of pro-neural glioblastoma it remains to be elucidated whether CSF1R inhibition in established BrM shows anti-tumor activity." (PMID 31396225, 2019). "Human glioblastoma frequently bear alterations of PI3K and PTEN, which might be associated with inherent resistance to CSF-1R targeting, readily explaining the results of this clinical trial." (PMID 31611871, 2019). "Similarly, treatment of glioblastoma with CSF1R inhibitor BLZ945 reprogrammed TAMs to an M1-like state." (PMID 30577495, 2018). "Finally, xenotransplants into the irf8−/− zebrafish mutant that lacks microglia, as well as pharmacological inhibition of the CSF-1 receptor (CSF-1R) on microglia, confirm a prominent role for zebrafish microglia in promoting human glioblastoma cell growth." (PMID 27779463, 2016). "Since the CD206/CD68 ratio increases in bevacizumab‐treated glioblastomas (“M2‐rich”), one may envision the application of CSF1R inhibitors in GBMs that recur after bevacizumab therapy." (PMID 26666269, 2016). "Interestingly, CSF-1R inhibition in mouse glioblastoma was shown to result in macrophage polarization as witnessed by decreased M2-type effector molecules and strong survival benefit of treated animals." (PMID 25110953, 2014).
glioblastoma (continued). "Further analysis revealed that macrophages expressing high levels of NT5E are characterized by elevated expression of chemokines and chemokine receptors such as CCR5, CCR2, ITGAV/ITGB5, and CSF1R, which may play a role in the recruitment of macrophages into the glioblastoma microenvironment." (PMID 40191733, 2025). "Using genetic mouse models of glioblastoma multiforme (GBM), researchers demonstrated that while the overall survival significantly increased in response to CSF-1R inhibition, tumors eventually recurred in over 50% of mice." (PMID 39457693, 2024). "Given both the role of radiation therapy in glioblastoma and the relationship between radiosensitivity and the macrophage profile identified in this study, a combination of CSF-1R inhibitor and irradiation may represent an effective approach to glioblastoma therapy." (PMID 35203505, 2022). "Thus, the increased immune cell infiltration by anti-CSF1R observed here might indicate a promising signal for improving the treatment efficacy of PD1 inhibition in glioblastoma." (PMID 34063518, 2021). "Indeed, this hypothesis is supported by a recent preclinical evaluation of a macrophage-targeted drug for treating glioblastoma multiforme (GBM) by antagonizing the colony stimulating factor-1 receptor on macrophages." (PMID 25905470, 2015). "They constructed a mouse model of intracranial in situ glioblastoma and administered whole brain irradiation at a dose of 12 Gy or in combination with PLX3397 (a small molecule CSF-1R tyrosinase activity inhibitor)." (PMID 40007537, 2025). "This approach suggests co-targeting PD-1 immunotherapy with colony-stimulating factor 1 receptor (CSF-1R) inhibitors to enhance CD8+ T-cell functionality and induce apoptosis in glioblastoma." (PMID 39337925, 2024). "Reduction of CD14dimCD16+ monocytes was shown in the PB of patients with glioblastoma treated with the highly selective CSF1R inhibitor PLX3397 and of patients with diffuse-type giant cell tumor treated with the anti-CSF1R antibody RG7155." (PMID 37013652, 2023). "Pexidartinib (PLX3397), the first commercial CSF1R inhibitor approved by the Food and Drug Administration (FDA), was recently used in a phase II clinical trial of recurrent glioblastoma (NCT01349036)." (PMID 36311702, 2022). "TAM repolarization and consequent tumor suppression were also observed after treatment with another CSF-1R inhibitor, PLX3397, in a mouse glioblastoma model." (PMID 34988021, 2021). "Taken together, our stainings detected CSF1R and markers for TAM and TILs in newly diagnosed and corresponding progressive glioblastoma samples." (PMID 34063518, 2021). "The biomimetic IL12/CSF1R‐macrophage membrane and c‐RGD‐decorated and PEGylated liposome synergistically achieved efficient blood–brain‐barrier crossing and tumor targeting, with efficient enrichment of nanovesicles in glioblastoma." (PMID 40279543, 2025). "Surprisingly, CSF-1R inhibition in the glioblastoma model does not reduce TAM numbers but alters their phenotype from pro-tumoral to anti-tumoral in response to tumor secretion of granulocyte macrophage (GM)-CSF." (PMID 39588367, 2024). "Sotuletinib (BLZ945) is a brain-penetrant, oral CSF1R inhibitor that has demonstrated a reduction in TAM recruitment, tumour growth, and resistance to programmed cell death 1 (PD-1) inhibitors in animal models of intracranial glioblastoma multiforme (GBM)." (PMID 37711590, 2023). "As reported, single-agent therapy with CSF-1R inhibitors has demonstrated only modest results in glioblastoma clinical trials, showing no significant improvement in the progression-free survival of patients." (PMID 35115369, 2022). "Accordingly, single-agent therapy with CSF-1R inhibitor has demonstrated very modest results in glioblastoma clinical trials, showing no significant improvement of the progression-free survival of the patients." (PMID 34950148, 2021).
glioblastoma (continued). "IL34, however, is downregulated in glioblastoma and thus does not play a significant role in CSF-1R signalling in glioblastoma." (PMID 33803414, 2021). "We conclude that a combined targeting of CSF1R and PD1 in future clinical trials might be feasible in newly diagnosed and as well as in RT/TMZ-treated progressive glioblastoma." (PMID 34063518, 2021). "In patients with recurrent glioblastoma treated with an oral CSF-1R inhibitor PLX3397, the percentage of non-classical monocytes (CD14loCD16+) declined after treatment but microglia in the tumor microenvironment were only modestly reduced." (PMID 31191529, 2019). "PD-1 and CSF-1R blockade in combination was also found to augment the cytolytic capacity of tumor infiltrating lymphocytes (TILs) in co-cultures of CD3+ TILs and CD11b+ tumor infiltrating myeloid cells from patients with glioblastoma." (PMID 31191529, 2019). "To the best of our knowledge, we first developed an efficient glioblastoma treatment paradigm of membrane‐targeted mild photothermal‐immunotherapy with lipophilic NIR‐II emissive probe (IRC18)‐loaded liposome and genetically engineered IL12/CSF1R‐macrophage membrane hybrid nanovesicles." (PMID 40279543, 2025). "Nevertheless, the impact of CSF-1R inhibition is not uniform across glioblastoma subtypes." (PMID 41479886, 2025). "In a phase II clinical study, treatment with CSF-1R inhibitors in recurrent glioblastoma patients failed to meet primary endpoint of 6 months PFS, which may be attributable to the high frequency of PTEN and PI3K pathway mutations among glioblastoma patients." (PMID 34054867, 2021). "Despite these promising preclinical studies, a phase 1b/2 clinical trial evaluating CSF-1R inhibition in combination with radiotherapy and temozolomide for newly diagnosed glioblastoma did not improve median PFS or overall survival compared to historical controls (NCT01790503)." (PMID 34054867, 2021). "Although CSF-1R inhibitors showed promising results in preclinical studies, the clinical trials with orally administered CSF-1R inhibitor PLX-3397 were negative, with minimal clinical efficacy in patients with recurrent glioblastoma." (PMID 33572835, 2021).
melanoma (77 papers, 2014 to 2025). A malignant, usually aggressive tumor composed of atypical, neoplastic melanocytes. "Epigenetic alterations in the CSF-1R promoter region induced CSF-1R up-regulation in melanoma cells with the BRAF mutation." (PMID 38254773, 2024). "Another study showed that depletion of colony-stimulating factor-1 receptor (CSF-1R) using siRNA in M2-like TAMs caused their depletion in the melanoma TIME." (PMID 35189921, 2022). "Similarly, an altered expression of CSF-1R was found in resistant melanoma cells with BRAF and MAPKs mutations." (PMID 38254773, 2024). "To date, a phase I/IIa clinical trial (NCT02452424) has evaluated the efficacy of this combination therapy—CSF1R and the immunotherapeutic agent pembrolizumab—in patients with solid tumors, including melanoma." (PMID 40918451, 2025). "Microglia that are recruited to the site of melanoma through CSF1R and TREM2 and are exposed to C3 adopt a supportive phenotype characterized by IL-10 and TGF-β release, extracellular matrix remodeling, synaptic pruning, and reduction in cytotoxic signals." (PMID 41463339, 2025). "Recent work highlighted a subset of F4/80hiCD115hiC3aRhiCD88hi TAMs that are recruited to melanoma tumors through the NF-κB1/CSF1R/C3aR axis." (PMID 39172519, 2024). "A study in an inducible CSF1R knockout mouse model of melanoma demonstrated that granulocytic myeloid-derived suppressor cells (G-MDSCs) persist following CSF1R blockade which depleted TAMs." (PMID 38533720, 2024). "They demonstrated that the inhibition of CSF-1R and IL-6 in melanoma and non-small cell lung cancer (NSCLC) prevented tumor-induced DCs switching and enhanced the T cell-mediated immune response." (PMID 39457693, 2024). "Analyses of previously published single-cell RNA sequencing (scRNA-seq) of tumor tissue samples from melanoma and colorectal cancer patients showed how both CSF1R and PD-L1 are particularly enriched in the myeloid populations infiltrating the human tumors." (PMID 37637207, 2023). "We assessed various dose levels of anti-CSF1R in murine melanoma models and studied the cellular and molecular effects." (PMID 37964379, 2023). "Nanoparticles loaded with anti-CSF-1R siRNA specifically depleted the M2-TAMs from melanoma and then restored the immune function of T cells, decreased the tumor size, and prolonged the overall survival." (PMID 35585567, 2022). "The combination of anti-PD1 and anti-CSF1 receptor (CSF1R) antibodies induced the regression of melanoma in-driven transplanted mice." (PMID 36531226, 2022). "PLX647 improves systematic immunosuppressive state by inhibiting CSF1/CSF1R signaling and has been shown to be effective in the treatment of breast cancer, melanoma and lung cancer." (PMID 36439090, 2022). "The combination therapy of agonistic anti-CD40 monoclonal antibody and CSF-1R inhibitor effectively inhibits tumor growth in mouse models of melanoma by targeting TAMs, transforming “cold” into “inflamed” tumor microenvironment." (PMID 35585567, 2022). "In the paracrine mode, macrophages that express the colony-stimulating factor 1 receptor (CSF1R) respond to CSF secreted by melanoma cells, which also stimulates resistance in autocrine manners." (PMID 36181568, 2022). "We compared their characteristics to the melanoma TAMs, evaluating the expression of CD11b, F4/80, Ly6C, CSF1R, iNOS, CD40, CD86, MHCII, Arg1, CD163 and CD206 expression by flow cytometry." (PMID 34572807, 2021). "In IDO-expressing melanoma and colon cancer, inhibition of CSF-1R signaling can functionally block tumor-infiltrating MDSCs and enhance antitumor T-cell responses, thus sensitizing IDO-expressing tumors to immunotherapy with T-cell checkpoint blockade." (PMID 35003065, 2021). "Our data interpretation is further supported by a recent study demonstrating that the combination of anti-PD1 and anti-CSF1R antibodies prolonged the survival of BRAFV600E-driven mouse melanoma." (PMID 34063518, 2021).